MIR7515 (microRNA 7515)
Synonyms: hsa-mir-7515
Gene: MicroRNA gene on chromosome 2 (6,650,373 to 6,650,439, forward strand). Ensembl gene ENSG00000283394.
Diseases named in the same sentence as MIR7515 in open-access papers:
MIR7515 is named in the same sentence as 1 disease in open-access papers, as found by Europe PMC text mining. Sharing a sentence is not in itself a finding about the gene and the disease. The quoted sentences say what the papers report.
cancer (1 paper, 2020). A tumor composed of atypical neoplastic, often pleomorphic cells that invade other tissues. "Six of these genes have been reported to be associated with cancers, including LOC284933, BOD1L2, MIR7515, ZNF729 and ZNF479, and MKL1." (PMID 32414326, 2020).